ALB (albumin)
Diseases named in the same sentence as ALB in open-access papers (continued):
Sharing a sentence is not in itself a finding about the gene and the disease.
COVID-19 (continued). "However, emerging evidence suggests that combining laboratory parameters with markers significantly involved in the cytokine storm may also help to predict the mortality risk in COVID-19 patients, mainly albumin and interleukin (IL)-15." (PMID 34683480, 2021). "The aim of the present longitudinal cohort study was to determine whether elevated CRP levels measured in the early stages of COVID-19 were associated, independently from the albumin levels, with higher 14-day mortality in geriatric patients hospitalized for COVID-19." (PMID 34506514, 2021). "The presented molecular analysis of the binding of dexamethasone to serum albumin in combination with the risk factors identified from the clinical data analyzed here and elsewhere offer promising strategies for maximizing the effectiveness of dexamethasone in the treatment of severe COVID-19." (PMID 33063792, 2020). "Albumin levels decreased with the progression of the disease and could be used as anindependent predictor (cut-off point: 35.1 g/l) of the risk ofnonsurvivors in critically ill patients with COVID-19." (PMID 32490680, 2020). "In conclusion, the risk factors for COVID-19 patients to develop from moderate to severe condition consists of: complicated common underlying diseases, respiratory frequency, lymphocyte count, blood glucose, albumin, urea, inflammatory factor (CRP, IL-6), and imaging manifestations." (PMID 33042873, 2020). "Training loads and the level of thiol-oxidised albumin were highest in the early pre-season and lowest at the conclusion of the pre-season, when training loads were reduced as a consequence of COVID-19." (PMID 41812060, 2026). "This study aimed to investigate the association between baseline electrolyte disturbances and clinical outcomes in patients with COVID-19, with a particular focus on albumin-corrected calcium levels." (PMID 42195166, 2026). "Our analysis revealed markedly lower levels of albumin and significantly higher levels of GlycA in the severe COVID-19 patient group than in the moderate COVID-19 patient group." (PMID 40399692, 2025). "This biomarker picture of raised LDH, ferritin, urea, and TNT, but lower HB and albumin, has been extensively described in COVID-19 patients requiring admission to the CCU23,24." (PMID 41286140, 2025). "Among the numerous laboratory parameters routinely used in ICU settings, serum albumin and D-dimer have individually been shown to provide prognostic insights in various acute conditions, including sepsis, COVID-19, and trauma-related complications." (PMID 40507678, 2025). "It has been reported that the neutrophil-to-albumin ratio (NAR) can be a simple marker for predicting mortality in patients with COVID-19." (PMID 40002608, 2025). "We termed this score the CARRA-VID score (CRP to Albumin Ratio, Red blood cell distribution width, and age-based score for prognostication of hospitalized COVID-19 patients)." (PMID 40431641, 2025). "For example, in COVID-19 cohorts, low serum albumin levels combined with high D-dimer concentrations have been associated with more severe clinical presentations and higher mortality." (PMID 40507678, 2025). "In COVID-19 patients, TP and ALB levels drop below the lower limit of the reference range (TP: 65-85 g/L, ALB: 40-55 g/L), while globulin (GLB) levels remain within the reference range (20-40 g/L)." (PMID 40046064, 2025). "The serum albumin decreased less than in COVID-19 patients, where the average time from the disease onset to indications for invasive mechanical ventilation was longer." (PMID 40017475, 2025). "Our analysis revealed routine chemistry assays, including renal and liver function test results, such as higher glucose, lower albumin, and higher AST levels, are associated with severe COVID-19." (PMID 40506946, 2025).
COVID-19 (continued). "Factors associated with worse outcomes in both COVID-19 and non-COVID-19 patients included decreased hemoglobin, increased leukocyte count, decreased LY-SSC, increased LY-FSC, widened LY-SFL, increased MO-SSC, decreased albumin levels, and elevated AST levels." (PMID 40506946, 2025). "A high serum albumin level is also associated with fewer adverse outcomes, less ARDS development, and less ICU admission in COVID-19." (PMID 40130722, 2025). "The CRP/albumin ratio (CRP/A) emerged as a significant marker in our study for highlighting lung involvement in COVID-19 patients." (PMID 40428888, 2025). "Nonetheless, the consistent inverse correlation between albumin and pro-inflammatory cytokines, alongside its decline over time, reinforces its role as a marker of systemic illness and poor prognosis in COVID-19." (PMID 40649865, 2025). "The decrease in lactate dehydrogenase has been associated with cellular preservation and improved oxygenation, while the increase in albumin downregulates the expression of ACE2 and is inversely associated with COVID-19 severity." (PMID 39940787, 2025). "Urine-albumin creatinine-ratio (UACR) was elevated in patients with COVID-19 compared to healthy controls (males 8 times, females 4.5 times) with no sex-based difference." (PMID 39382598, 2025). "We discovered that patients with severe COVID-19 had a lower basal lymphocyte count and albumin level but higher D-dimer and ferritin levels." (PMID 39928605, 2025). "The median urine albumin:creatinine ratio at baseline was 72.1 mg/g (IQR 24.7–143.7) in COVID-19 patients and 48.2 mg/g (IQR 21.9–197.9) in control patients." (PMID 38464257, 2024). "While patients with COVID-19 experience a cytokine storm; TC, HDLc, ApoA1, albumin, total protein levels decrease as well as CD16+ T, CD3+ T, and CD8+ T cell counts." (PMID 38753890, 2024). "The reported abnormal levels of ROS and OS suggest a high degree of structural changes in the protein molecule, formation of non-functional protein derivatives, and high concentration of oxidized albumin in COVID-19." (PMID 39125614, 2024). "Other lab parameters such as lymphopenia, coagulation abnormalities, and decreased levels of albumin have also predicted COVID-19 mortality." (PMID 38639116, 2024). "In comparison, the lowest albumin levels detected in COVID-19 patients can be relatively easily elevated above the threshold when necessary." (PMID 39612427, 2024). "The total bilirubin (TBIL), direct bilirubin (DBIL), and prothrombin time (PT) were higher than the normal ranges in ACLF+COVID-19 patients, whereas the albumin (ALB) level was below the minimum thresholds." (PMID 39867341, 2024). "Elevated CRP, ferritin, and NLR levels were consistently observed in positive cases, while albumin levels were lower, aligning with known clinical characteristics of COVID-19." (PMID 39767161, 2024). "This review presents the interrelationship between oxidative stress, inflammation, and low albumin levels, which are hallmarks of COVID-19." (PMID 39125614, 2024). "Laboratory indicators at the time of COVID-19 diagnosis, including hemoglobin, albumin, lactate dehydrogenase, and C-reactive protein (CRP), showed substantial differences between the patients who survived and those who died." (PMID 38172385, 2024). "IL-34, CRP, D-dimer, TnI, and ferritin levels were statistically significantly higher; albumin levels were statistically significantly lower in the COVID-19-positive group compared to the control group (p<0.05)." (PMID 38626032, 2024). "In this study, we determined the profile of traditional biomarkers of inflammation, including CRP, albumin, complete blood count, and neopterin levels, in patients with COVID-19 admitted to the intensive care unit (ICU) and in healthy volunteers." (PMID 39058886, 2024). "An albumin to creatinine (ACR) ratio was comparable between the COVID-19-positive participants and the COVID-19-negative participants." (PMID 39861814, 2024).
COVID-19 (continued). "The high levels of ROS, the oxidized form of albumin, and low levels of protein can make it impossible to obstruct COVID-19 induced oxidative injury and lead to large-scale organ damage." (PMID 39125614, 2024). "Previous studies showed that in COVID-19, serum albumin is seriously reduced during the acute phase of the disease and correlated with mortality and thrombotic events." (PMID 39456513, 2024). "In the study comprising 275 patients diagnosed with COVID-19, patients exhibiting a C-reactive protein/albumin ratio (CAR) between 1.56 and 11.19 demonstrated an eight-fold increased risk of mortality relative to those presenting with a CAR below 0.29." (PMID 39164612, 2024). "Systematic reviews and meta-analyses have shown that serum albumin concentrations are significantly lower in COVID-19 patients with higher disease severity." (PMID 38494528, 2024). "Elevated levels of CRP and reduced albumin levels are crucial indicators of severe disease progression, indicating the development of cytokine storm in COVID-19 patients." (PMID 37712883, 2024). "Our study showed that decreased albumin levels play an important role in the assessment of the severity of COVID-19 and survival in cardiovascular patients, which correlates with findings from a previous study." (PMID 39119143, 2024). "On the other side, elevated urea indicates misfunction of kidney metabolism and is related to COVID-19 severity, alone or along with the albumin as a ratio." (PMID 38500972, 2024). "Serum neopterin, C-reactive protein (CRP), albumin levels, and complete blood count were determined in 39 patients with severe COVID-19 and 30 healthy individuals." (PMID 39058886, 2024). "This suggests that clinicians should be alert to liver injury in patients with COVID-19, and should pay attention to changes of albumin and other markers of liver function to improve the long-term outcome of these patients." (PMID 38783947, 2024). "The reported abnormal levels of ROS and OS suggest a high degree of structural changes in the protein molecule, the formation of non-functional protein derivatives, and a high concentration of oxidized albumin in critical COVID-19." (PMID 39125614, 2024). "Coronavirus Disease-2019 (COVID-19) caused by the severe acute respiratory syndrome Coronavirus 2 (SARS-CoV-2), as a cause of viral sepsis, could justify the possibility of similar responses to lactate and albumin values." (PMID 39685564, 2024). "It was determined through single-factor regression analysis that age, WBC count, neutrophil count, ALB, urea nitrogen, CR, UA, RDW-CV, RDW-SD, hemoglobin, MCH, and MCHC were independent risk factors associated with death from COVID-19 (p < 0.05)." (PMID 38741698, 2024). "In this study, we evaluated the effectiveness of the lactate/albumin ratio for mortality prediction in a large cohort of patients with severe COVID-19 admitted to the ICU." (PMID 39685564, 2024). "We observed significantly reduced levels of TP, PA, and ALB in individuals with COVID-19 compared to the control group." (PMID 38464514, 2024). "Laboratory findings from a retrospective study of COVID-19 patients in China demonstrated a decrease in the albumin and lymphocyte count and an elevation in the WBC count, ALT, AST, LDH, CRP, and serum creatinine." (PMID 39995847, 2024). "Some asymptomatic patients displayed indicators consistent with the healthy population, while patients with severe COVID-19 symptoms exhibited lower ALB and globulin levels." (PMID 38303719, 2024). "In various studies, low albumin levels have been shown to be a predictor of severe morbidity and mortality in COVID-19 patients." (PMID 39064471, 2024). "Adequate albumin levels appear to be key since albumin displays antioxidant properties, such as scavenging oxygen free radicals, and the COVID-19 patients with higher albumin levels on admission were associated with a better overall prognosis." (PMID 38248379, 2024).
COVID-19 (continued). "According to a study conducted in Korea involving 1952 COVID-19 patients, a statistically significant decrease in albumin levels was observed in patients with severe and moderate disease compared to those with mild disease (P < 0.001)." (PMID 37712883, 2024). "The high levels of ROS and RNS generated during the acute phase of COVID-19 can lead to irreversible oxidative damage to albumin and impairment of its antioxidant properties." (PMID 39125614, 2024). "Disease mortality due to COVID-19 showed a significant inverse correlation with albumin and Ca levels in our study." (PMID 38618472, 2024). "Correlation analyses among these inflammatory biomarkers showed a correlation between neopterin levels and CRP and albumin levels in COVID-19 patients." (PMID 39058886, 2024). "Previous studies showed that low albumin levels are a predictor of severe morbidity and mortality in COVID-19 patients." (PMID 38674175, 2024). "Different inflammatory markers such as NLR, CAR, MLR, PLR, albumin/globulin ratio, and the PNI and SII were evaluated in many studies in terms of their use for COVID-19 risk stratification." (PMID 39124732, 2024). "Our model suggested that the CRP to albumin ratio (CAR) is the most important determinant of COVID-19 severity." (PMID 38690475, 2024). "In line, E-selectin, IL-8, and MCP-1 levels were significantly higher, while albumin levels were lower in the most severe COVID-19 patients." (PMID 38494528, 2024). "COVID-19 cases exhibited substantially lower levels of TP, PA, and ALB, with the most severe patients displaying the lowest levels of these proteins." (PMID 38464514, 2024). "Upon admission, a lower nutritional prognostic index and higher CRP/TTR and CRP/Albumin ratios were related to a higher probability of developing severe COVID-19." (PMID 39125329, 2024). "One study demonstrated that increased neutrophil, CRP, procalcitonin, AST, ALT, and total BIL values and decreased lymphocytes, platelets, and albumin values have a prognostic value for COVID-19." (PMID 39473741, 2024). "Most blood markers were significantly associated with all-time mortality in COVID-19 patients, with the strongest association with peak CRP level, CRP on admission, and lowest albumin level (p < 0.001 for all)." (PMID 39266635, 2024). "Markers such as ferritin, D-dimer, LDH, liver enzymes (ALT, AST, GGT, alkaline phosphatase (ALP), and total bilirubin), and kidney functions (creatinine, albumin, and total serum protein) are also monitored in patients suffering from COVID-19." (PMID 38398867, 2024). "In this study, similarly, serum albumin levels were found to be significantly low in the patient group with COVID-19." (PMID 39064471, 2024). "Significant differences were observed in age, CT score, ICU admission or intubation, length of stay, CRP at admission, albumin levels at admission between severe and moderate COVID-19 patients (P<0.05)." (PMID 39211792, 2024). "For COVID-19 patients, C-reactive protein/albumin ratio (CAR) represented an independent predictive biomarker for in-hospital mortality." (PMID 39148011, 2024). "The strong predictive value of CAR suggests that combining CRP with serum albumin enhances the assessment of inflammatory status and nutritional condition, which are critical factors in the prognosis of COVID-19 patients." (PMID 39767616, 2024). "Markers that were significantly lowered in the MIS-C training cohort compared to the COVID-19 training cohort are albumin (median 3.3 g/dL, p = 9.7×10−7), platelet counts (median 158/μL, p = 7.0×10−7) and sodium (median 134, p = 2.5×10−7)." (PMID 37685502, 2023). "It has been also shown that age, serum lactate dehydrogenase (LDH), CRP, red blood cell distribution width (RDW), blood urea nitrogen (BUN), albumin, and direct bilirubin can be used as accurate prognostic indicators for COVID-19 patients." (PMID 38130539, 2023).
COVID-19 (continued). "Decreased albumin level was more common among patients with COVID-19 (27% vs. 4.3%; Chi-squared = 5.457, p = .019)." (PMID 37501590, 2023). "Many studies showed impaired cell-mediated immunity, decreased phagocytes, complement system, lymphocytes, and T cell count among patients with critical COVID-19 and low albumin levels." (PMID 37867496, 2023). "Clinical data of serum albumin levels in clinically healthy volunteers—control group (Group 1) and in patients with COVID-19 (Group 2)." (PMID 36982882, 2023). "Albumin cytological dissociation was observed in 15 (83.3%) patients with COVID-19 vs. 34 (57.63%) patients in the other group, p = 0.0.180." (PMID 37483451, 2023). "Rizo-Tellez reported the IL-15/albumin ratio as a predictor of mortality with a cut-off value > 105.4 in hospitalized COVID-19 cases." (PMID 38006008, 2023). "Our results are in agreement with other authors whose research shows that high CRP and low albumin values are important for the development of a severe form of the disease, indicating the development of cytokine storms in patients with COVID-19." (PMID 37510752, 2023). "In patients with COVID-19, pH = 7.01 ± 0.06 (acidosis), suggesting a high percentage of oxidized albumin." (PMID 36982882, 2023). "In the moderate-severe group, the closest neighbors of COVID-19 severity were ferritin, fibrinogen, albumin, quantity of lymphocytes, scoring index of chest x-ray, white blood cell count, lactate dehydrogenase, and quantity of neutrophils." (PMID 36668902, 2023). "We also demonstrated the interrelations of the serum levels of vitamin D, albumin, and D-dimer in patients with COVID-19 as well as their significance as predictors of the outcome of the disease." (PMID 37109161, 2023). "White blood cells, basophils, monocytes, neutrophils, lymphocytes, eosinophils, aspartate aminotransferase (AST), alanine transferase (ALT), albumin and other clinical markers have proven to be important for COVID-19 diagnosis." (PMID 37436038, 2023). "In our study, ferritin and albumin are also among the most important immunological and metabolic biomarkers identified for COVID-19 mortality prediction." (PMID 38014372, 2023). "We are not aware of any published studies aiming to evaluate vitamin D, albumin, and D-dimer as prognostic factors of COVID-19 severity and outcomes." (PMID 37109161, 2023). "Of those peptides, 14 were from albumin and their decrease is in line with the well-documented decrease in albumin levels in COVID-19 patients." (PMID 36674321, 2023). "Statistically significant differences have been found in esterase status and biochemical indices (including albumin levels) between healthy subjects and patients with COVID-19, as well as between surviving and deceased patients." (PMID 37373530, 2023). "Fibrinogen concentrations were significantly raised, and albumin levels were significantly lowered in patients with severe COVID-19 when compared with moderate." (PMID 37554121, 2023). "eGFR (43.6 ± 26.5 mL/min vs. 79.7 ± 31.1 mL/min/1.73 m2, p < 0.001) and serum albumin levels (29.3 ± 6.2 g/L vs. 36.8 ± 6.4 g/L, p < 0.001) were lower in COVID-19 patients with hypernatraemia compared with those with normonatraemia." (PMID 36769690, 2023). "Research encompassing biomarkers for predicting COVID-19 patient outcomes is rapidly increasing, and higher albumin levels upon admission have emerged as predictors of better prognosis in hospitalized patients with confirmed COVID-19 infection." (PMID 37762957, 2023). "Biochemical parameters, especially Urea, Sodium, Indirect bilirubin, AST, PCT and Albumin can be used to predict the requirement of type of ventilation in management of severely ill COVID-19 patients." (PMID 37969877, 2023). "We examined the significance of the serum concentrations of vitamin D, albumin, and D-dimer for the severity of the clinical picture and mortality in COVID-19." (PMID 37109161, 2023).